CX3CL1 (C-X3-C motif chemokine ligand 1)
Diseases named in the same sentence as CX3CL1 in open-access papers (continued):
Sharing a sentence is not in itself a finding about the gene and the disease.
tumor (continued). "Conversely, the CX3CL1/CX3CR1 axis has been shown to promote cancer cell proliferation, migration, and invasion, along with recruiting pro-tumor immune cells." (PMID 38775151, 2024). "We examined the secretion of CX3CL1 from MTX-treated cancer cells undergoing immunogenic apoptosis and its potential role as a mediator of anti-tumour immunity during ICD." (PMID 39011040, 2024). "Our study revealed that CX3C motif chemokine ligand 1 (CX3CL1) had a higher expression in the metastatic phenotypic cancer mouse OSCC 2 (MOC2) than in MOC1, which had a localized tumor phenotype." (PMID 38775151, 2024). "CX3CL1 is the only member of the CX3C chemokine family and is constitutively expressed in a variety of cells, including epithelial tumor cells." (PMID 37968706, 2023). "Overexpressed CX3CL1 attracted CD3‐CD49b+ NK cells, CD3+CD4+ T cells, and CD3+CD8+ cytotoxic T cells to tumor tissues in the 4T1 animal model, whereas regulatory T cells, F4/80+MHC II+ macrophages, and CD11b+ cells did not significantly change." (PMID 36794651, 2023). "CX3CL1/CX3CR1 signaling is constantly activated in the process of monocyte recruitment and subsequent differentiation to TAMs in the tumor niche." (PMID 37968706, 2023). "We treated CT26 tumor cells with IFN-γ, and TNF-α followed by treatment with CX3CL1 and obtained comparable results wherein CX3CL1 induced robust expression of genes that promote tumor immune-resistance and generate a pro-metastatic niche." (PMID 37771579, 2023). "Tumor cells which express CX3CL1 can induce the invasion and metastasis of CX3CR1-positive tumor cells." (PMID 37770496, 2023). "Expression of chemokine receptors that match ligands secreted by the tumor such as CCL2, CCL22, CXCL16, CX3CL1, CXCL1 and CXCL8 can enable CD8+ T cells to enter the tumor." (PMID 37301772, 2023). "Inhibition of nSMase2 decreased the expression of VCAM1, CX3CL1, and CXCL10 by ECs and reduced T cell tumor infiltration." (PMID 36901858, 2023). "CX3CL1 upregulates ICAM‐1 expression through the proposed CX3CR1/PLCβ/PKCα/s‐Src/AP‐1 signalling pathway and subsequently promotes tumour metastasis." (PMID 37082943, 2023). "The reprogrammed cancer cells then present the tumor antigens to CD4+ Tfhs via MHC-II and release CX3CL1 to recruit NK cells, PMos and cDC2s." (PMID 36869384, 2023). "Numerous reports suggest that CX3CL1 can effectively recruit NK cells and T cells into the TME and is a key promoter of anti-tumor activity." (PMID 36397015, 2022). "In GCT cells, miR‐125b expression in tumor cells promoted a microenvironment enriched with TAM via increasing the production of tumor‐derived chemokines CSF1 and CX3CL1 for TAM recruitment." (PMID 35811571, 2022). "In EBV-positive NPC cells, activated NF-kB regulates a number of chemokines (CXCL9, CXCL10, CX3CL1, and CCL20), which recruit tumor-infiltrating T lymphocytes and modulate the NPC tumor environment." (PMID 36289760, 2022). "Lysates of MTX-treated 9464D tumors displayed a more than 2.5-fold increase of IL1a, CXCL16, FLT3L, CX3CL1 and IL1RA, and a more than 1.5-fold increase of CXCL10, CXCL5, CCL5 and CXCL9 compared to control tumor lysates." (PMID 36397148, 2022). "To analyze the mechanism by which CX3CL1 and CX3CR1 regulate liver metastasis, we first assessed CX3CR1 expression in tumor cell lines." (PMID 35478937, 2022). "On the contrary, anti-tumour chemokines, such as CCL14 and CX3CL1, were related to low NEIL3 expression in most cancers." (PMID 36612106, 2022). "The mir-561-5p/chemokine (C-X3-C motif) ligand 1 (CX3CL1)/natural killer (NK) cell axis drives HCC metastases and shows that CX3CR1+ NK cells act as the strong anti-tumor therapeutic factors." (PMID 35215154, 2022). "Here, we evaluated the anti-tumor activity of a combined trastuzumab and TMI-1/GI254023X treatment in the context of CX3CL1 expression." (PMID 34070094, 2021).
tumor (continued). "In contrast to the soluble variant, the membrane located CX3CL1 with its physiological function as adhesion molecule promotes stronger adhesion of leucocytes to CX3CR1-positive cells, and therefore, might enhance T cell killing or NK cell mediated ADCC on trastuzumab coated BC tumor cells." (PMID 34070094, 2021). "CX3CL1 is TP53AIP1, and Fas and DR5 act as tumor suppressors by promoting cell apoptosis or inhibiting cell migration 31-34." (PMID 34131400, 2021). "For example, the expression of CX3CL1 has been confirmed to result in the infiltration of NK cells, DCs, CD4+, and CD8+ T cells into the tumor, which leads to an increase in the antitumor immune response." (PMID 35140706, 2021). "The result shows that in tumor cells, PMEPA1 were negatively correlated with some chemokines (including CXCL1, CXCL11, CXCL2, CXCL8, CX3CL1) and positively correlated with CXCL14 and LAG3." (PMID 34777336, 2021). "Some upregulated genes, such as CX3CL1 31, TP53AIP1 32, Fas 33, and DR5 34, were reported as tumor suppressors." (PMID 34131400, 2021). "Next, we investigated the effect of CX3CL1 expression and the impact of ADAM inhibitors using the humanized tumor mouse model (HTM), which allowed the investigation of the impact of CX3CL1 on tumor growth, metastatic spread and human immune cell modulation." (PMID 34070094, 2021). "The mRNA levels of TEK, BMP1, AR, SLC11A1, SLC40A1, and F2RL1 were significantly downregulated in tumor cells compared with normal cells, and CX3CL1 and RNASE2 were upregulated in tumor cells." (PMID 35004689, 2021). "This would confirm the assumption of CX3CL1 as a trigger for the activation of effector cells and promotor for stronger adhesion of leucocytes to CX3CR1-positive tumor cells as postulated before." (PMID 34070094, 2021). "An increased expression of CX3CL1 in a cancer cell leads to the infiltration of NK cells, dendritic cells, CD4+ and CD8+ T cells into the tumor." (PMID 32466280, 2020). "Other chemokines and their receptors with a central role in MSC tumor homing are C-C motif chemokine receptor 1 (CCR1), CCR7, CCR9, C-X3-C motif chemokine ligand 1 (CX3CL1), CXCR5, and CXCR6." (PMID 33117154, 2020). "Their migration to inflamed tissues including tumor sites involves a series of chemokine receptors such as CCL3-5/CCR5, CXCL10/CXCR3, and CX3CL1/CX3CR1." (PMID 31991604, 2020). "In the tumor niche, the CX3CL1-CX3CR1 axis plays an important anticancer role as it allows for the migration of immature dendritic cells to the cancer cell using CX3CL1 expression." (PMID 32466280, 2020). "These two chemokines have been involved in the regulation of tumoural neovascularisation, CXCL10 being usually described as an inhibitor of angiogenesis, whereas CX3CL1 has pro-angiogenic effects." (PMID 32946040, 2020). "CX3CL1 is a chemokine induced by inflammatory cytokines such as TNFα, IL-1β, and IFN-γ and its role is to recruit immune cells at tumor sites and to boost antitumor immune responses." (PMID 30108590, 2018). "Our study suggests that miR-125b in tumor cells regulates the production of CSF1 and CX3CL1 for recruiting macrophages to the neoplastic sites." (PMID 30237497, 2018). "Collectively, miR-125b abundance in tumor cells determines TAM recruitment at least partly by regulating chemokine CSF1 and CX3CL1 directly and/or indirectly." (PMID 30237497, 2018). "These genes included tumor markers (MUC16), genes that control tumor migration (MYL9), metastasis (CEACAM6, VEGFC, CX3CL1, CST1, CCL5, S100A9, IGF1, NOTCH3), cell adhesion (FN1, CEACAM1), and inflammation (TRAF2, NF-κB2 and RelB)." (PMID 26090868, 2015). "As apparent from this review, the CX3CL1/CX3CR1 axis promotes inflammation and tumor growth in the majority of disease models discussed." (PMID 24799766, 2014).
tumor (continued). "In a murine model, Tang and colleagues showed that transfer of the CX3CL1 gene into tumor cells elicited tumor-specific cytotoxic T cells and increased production of IL-2 and IFN-γ in tumor tissue leading to inhibition of HCC growth." (PMID 24799766, 2014). "Intriguingly, CX3CL1 down-modulation was observed in MYCN-amplified primary NB tumors, supporting a role in limiting tumor aggressiveness." (PMID 22253825, 2012). "CX3CL1, AGT, ATP1A2, and IGSF1 mRNAs proved to be significantly down-modulated in the BM-infiltrating GD2 positive fractions compared to primary tumor cells (P<0.0001, P = 0.0325, P = 0.0196, P = 0.0047, respectively)." (PMID 22253825, 2012). "By contrast, CX3CL1 and GILZ immunoreactivities in tumor cells were higher for the group with the higher level of proliferation." (PMID 21750716, 2011). "More specifically, normal cells adjacent to thetumour (Norm) were characterized by a lower expression of the tumour suppressorgene LOX, the receptors for interleukin 1(IL1R) and TGFβ(TGFBR) and by a higher expression of the pro-tumour genesCYR61 and CX3CL1." (PMID 21479216, 2011). "In this study, we unveiled that CX3CL1 was constitutively produced in EOC and investigated the role of this chemokine in tumor growth." (PMID 21750716, 2011). "In tumor specimens from 54 women who underwent surgical treatment for EOC diagnosis, CX3CL1 immunoreactivity was unevenly distributed in epithelial tumor cells, and ranged from strong (33%) to absent (17%)." (PMID 21750716, 2011). "In MOC2 tumors, CX3CL1 promoted the metastasis of cervical lymph nodes (LNs), increased the formation of tumor vascular-like structures (VLS), and significantly increased the invasion of tumor cells within VLS, indicating its pro-metastatic effect." (PMID 41445742, 2025). "Thus, chemokines such as CX3CL1, CCL5, and CXCL1 are involved in the actions of EVs-mediated premetastatic niche formation, enhanced tumor invasion, and modulated immune responses." (PMID 40103824, 2025). "In accordance with our in vitro data, enhanced proliferation did not seem to account for the accelerated tumour outgrowth upon Cx3cl1 overexpression, as Ki67-positivity was unaltered in Cx3cl1+ tumours (median 37 % vs 36 % of total cells; P = 0.76)." (PMID 39862711, 2025). "Furthermore, CX3CL1 induces innate and adaptive immunity, including the recruitment of effector cells of CD57+ lymphocytes to tumor tissues." (PMID 41445742, 2025). "We also focused on other biomarkers playing an important role in tumor formation and growth, such as angiogenic factor VEGF (vascular endothelial growth factor), GDNF (glial cell derived neurotrophic factor) and chemokine fractalkine/CX3CL1." (PMID 39796185, 2025). "Although gene therapy involving the transfer of CX3CL1 to cancer cells was demonstrated to induce a robust anti-cancer effect, we did not see a significant reduction in tumour size following co-treatment with CX3CL1 and MTX in the therapeutic mouse model." (PMID 39011040, 2024). "To this end, we used Pmel-1 TCR transgenic CD8+ T cells that can recognize gp100 expressed on B16 tumor cells lacking CX3CL1 expression and evaluated the potential intratumoral differentiation of tumor-specific CD8+ T cells." (PMID 38881188, 2024). "Also, BDNF, GDNF, NGF, and axon guidance molecules, such as CX3CL1, EphA2, CCL2, Slit, and so forth, are groups of neuroactive chemicals generated by the nerves involved in tumor–nerve interaction." (PMID 39346791, 2024). "The observation that T cell abundance and PD-1 expression did not change in Vhl Cx3cl1–DKO tumors compared with Vhl-KO tumors suggests that Vhl loss facilitates multiple mechanisms to affect the microenvironment and the tumor response to ICB." (PMID 38618956, 2024).
tumor (continued). "In a xenograft mouse model, CX3CL1 knockdown cells had significantly lower tumor weights compared to the negative control." (PMID 39409924, 2024). "Interestingly, when CX3CL1 enrichment was seen in patients with OSCC, higher lymphatic structures were found near the invasive front of the primary tumor in OSCC samples." (PMID 38775151, 2024). "Except for CXCR6, all cytokines/cytokine receptors were shown to operate in the spine, with CX3CL1, CX3CR1, IL10, CCL2, CXCL12, and CXCR4 mediating bone marrow colonization, CXCL5 and TGFβ promoting tumor cell proliferation, and TGFβ additionally driving bone remodeling." (PMID 36835198, 2023). "The results demonstrated upregulation of CX3CL1 and INHBB expressions in tumor tissues." (PMID 37886241, 2023). "CX3CL1 is another member of the chemokine CXC subfamily, which can bind to CX3CR1 that is highly expressed on macrophages, and increase the accumulation of macrophages in tumor tissues." (PMID 36794651, 2023). "UTMD could trigger the expression of chemokine (C-X3-C motif) ligand 1 (CX3CL1), thus attracting NK-92MI cells into the tumour regions." (PMID 36463323, 2023). "In addition, neutral sphingomyelinase 2 (nSMase2)-dependent EC activation has been shown to express chemokines, CX3CL1 and CXCL10, as well as the adhesion molecule VCAM1, to promote T cell migration into the tumor bed." (PMID 36901858, 2023). "In serum of CT26 tumor-bearing mice, there was extensive overlap with the factors detected in CT26-conditioned media: following mediators identified in conditioned media showed at least a 1.2-fold increase in CT26 tumor-bearing mice: IL-1α, IL-2, IL-13, CCL2/5/19, LIX, CX3CL1, CXCL1/2/10 and CCL19." (PMID 35962398, 2022). "Meanwhile, overexpression of ICAM-1 also significantly increased the number of adhered tumor cells and reversed the adhesion disadvantages of NSCLC cells conferred by CX3CL1-KD treatment in the presence of platelets, highlighting the dependent role of ICAM-1 in platelet-assisted NSCLC cell adhesion." (PMID 33754027, 2021). "CX3CL1, also known as fractalkine, is an inflammatory chemokine with the single receptor CX3CR1 which regulates cytotoxic T cell-mediated immunity by recruiting TIL (tumor-infiltrating lymphocytes) to the tumoral microenvironment." (PMID 34771699, 2021). "The application of the ADAM inhibitors TMI-1 as well as GI254023X blocked CX3CL1 shedding in vitro but without affecting the tumor cell viability or proliferation." (PMID 34070094, 2021). "TMI-1 and GI254023X caused a reduced shedding of CX3CL1 and of HER2 in vitro but without effects on tumor cell proliferation or viability." (PMID 34070094, 2021). "Irrespective hereof, other authors described an enhanced tumor growth due to the stimulation of angiogenesis by CX3CL1, which was not examined in HTM." (PMID 34070094, 2021). "This may be partly due to other tumor-derived factors also attract circulating monocytes to the tumor site and differentiate into TAMs, such as CSF1, CCL5, CXCL12 and CX3CL1." (PMID 33564072, 2021). "Soluble CX3CL1 might also bind to CX3CR1 expressing tumor cells and trigger tumor cell proliferation." (PMID 34070094, 2021). "In MDA-MB-453CX3CL1–based HTM, TMI-1 treatment resulted in a slightly increased tumor growth in comparison to MDA-MB-453empty-based HTM, which suggests a pro-proliferative effect of membrane-bound CX3CL1 or the missing anti-proliferative effect of the soluble form." (PMID 34070094, 2021). "Their interaction with the BMDMs and tumor cells in the collagen-I matrix increased production of GM-CSF, G-CSF, IL-6, CCL2, CCL3, CCL4 and CCL12, and reduced production of IFN-β1, LIF, VEGF, CCL17, CXCL5 and CX3CL1." (PMID 34572807, 2021). "Increased expression of CX3CL1 and CX3CR1 in a tumor is both anti-cancer and pro-cancer." (PMID 32466280, 2020). "CX3CL1 was the ligand of chemokine CX3CR1, which could promote tumor infiltrating cells into tumor microenvironment and play the role of immunotherapy." (PMID 32780567, 2020).
tumor (continued). "Furthermore, in HCC patients, CX3CL1/CX3CR1 regulates the cancer cell cycle and tumor progression via the autocrine or paracrine systems, which is associated with positive outcomes." (PMID 31991604, 2020). "This process is significant in a GBM tumor, characterized by high expressions of CX3CR1 and CX3CL1." (PMID 32466280, 2020). "Interestingly, these pathways are utilized by a series of chemokines and their receptors, such as CCL20/CCR6, CCL25/CCR9, CXCL1/CXCR2, CXCL8/CXCR1-2, CXCL12/CXCR4, and CX3CL1/CX3CR1, to inhibit apoptosis and promote tumor cell growth and proliferation." (PMID 31991604, 2020). "Thus, in this study, we hypothesized that CX3CL1 induced the formation of stress fiber, the ZO-1 disruption in VMECs and then promoted VMECs barrier disruption, which further mediated vertebral micro-vascular hyper-permeability and increased tumor cell TEM in the spine." (PMID 32390803, 2020). "We found that incubation VMECs with CX3CL1 significantly increased the migration rate of cancer cells and that inhibiting Src/P115-RhoGEF/ROCK signaling in VEMCs effectively blocked the process of tumor cell TEM." (PMID 32390803, 2020). "Tumor cell MVs promote MMP-9 and ERK1/2 phosphorylation in fibroblasts to induce chemoresistance and migration; in turn activated fibroblasts secrete MVs carrying CX3CL1 that more strongly promote migration/invasion of cancer cells expressing CX3CR1." (PMID 32957712, 2020). "The average tumor size and pulmonary metastasis rate were decreased in mice treated with CX3CR1+ NK cells alone relative to those treated with CX3CR1+NK cells combined with an anti-CX3CL1 antibody or an anti-CX3CR1 antibody." (PMID 31367257, 2019). "In contrast, we were not able to show a tumor cell intrinsic function of the chemokine but confirmed through a genome-wide unbiased approach that NF-κB/RelA regulates the expression of CX3CL1 in PDAC tumor cells." (PMID 31561620, 2019). "Indeed, the CX3CL1/CX3CR1 axis is involved in the interaction between tumor cells and the microenvironment by the regulation of tumor cell invasion, migration, and adhesion and promotes bone metastasis." (PMID 30845779, 2019). "Notably, HPK1 KD mice showed markedly increased pro-inflammatory pathways in response to priming with tumor antigens as shown by the enhanced related gene expression, e.g. S100A8, GZMB, NKp44, CXCL14, CX3CL1, CD1d2, KLRG1, CD11c, NLRP3 and MUC1." (PMID 30913212, 2019). "CX3CL1 activates the SRC/focal adhesion kinase (FAK) signaling pathway in cancer cells regulating their migration and invasion and facilitates bone metastasis of CX3CR1-expressing tumor cells." (PMID 30845779, 2019). "In fact, despite the fact that CX3CL1 expression does not correlate with the density of tumor-infiltrating macrophages, it has been shown that it promotes macrophage survival in tumor microenvironment contributing to tumor cell dissemination." (PMID 30591657, 2018). "This demonstrates that in the tumor microenvironment in these cells, it is CX3CL1/fractalkine with CX3CR1, but not viral US28, that are responsible for the migration of TAM and microglial cells." (PMID 29467963, 2018). "Chemokine axes, such as fractalkine (CX3CL1)/CX3CR1, C-X-C motif chemokine ligand 12 (CXCL12)/C-X-C chemokine receptor type 4 and 7(CXCR4/CXCR7), CCL2/CCR2, and CCL5/CCR5, are clearly involved in tumor progression." (PMID 30123112, 2018). "Here we report that the miR-125b can act through a different mechanism to control TGCT growth, as low miR-125b expression in tumor cells promotes a TAM-rich microenvironment via increasing the production of tumor-derived chemokine CSF1 and CX3CL1 for TAM recruitment." (PMID 30237497, 2018). "In conclusion, our study demonstrates that enforced miR-125b expression in NCCIT tumor cells can inhibit the production of tumor-derived chemokines (e.g., CSF1, CX3CL1), recruit less pro-tumorigenic macrophages to tumor sites, and ultimately suppress TGCT growth." (PMID 30237497, 2018).